MMP2 (matrix metallopeptidase 2)
Diseases named in the same sentence as MMP2 in open-access papers (continued):
Sharing a sentence is not in itself a finding about the gene and the disease.
gastric cancer (continued). "We proved that our tested combination of OM-86II with the anti-MUC1 antibody reduced only MMP-9, but not MMP-2 concentration in AGS gastric cancer cells." (PMID 34770912, 2021). "It should be emphasized that HWGF targeting MMP2 alone has no biological function to inhibit gastric cancer." (PMID 32576271, 2020). "Mechanistically, BCL-w increases the level of mitochondria-derived reactive oxygen species (ROS), which is followed by SRC-mediated phosphorylation of EGFR145, and the activation of PI3K/AKT/Sp1 signaling pathway to increase MMP2 expression in GBM and gastric cancer cells." (PMID 32317622, 2020). "Secreted matrix metallopeptidase-2 (MMP-2) and urokinase plasminogen activator surface receptor (uPAR) have been demonstrated to activate focal adhesion kinase (FAK), which acts as an executioner of BCL-w-dependent invasive phenotype of gastric cancer cells." (PMID 32317622, 2020). "Simultaneously, we examined the expressions and activities of MMP-2 and MMP-9 after LOX inhibition and exogenous LOX treatment in gastric cancer cells, and analyzed the effect of LOX inhibition on PDGFR in the PDGF-PDGFR signaling pathway in gastric cancer cells." (PMID 31777578, 2019). "Furthermore, bufalin inhibited ASCL2 expression and down-regulated the expression of invasion-related genes such as MMP2, MMP9, and vimentin, thereby suppressing epithelial-mesenchymal transition (EMT) in gastric cancer." (PMID 29805736, 2018). "Gelatin zymography assay further indicated the activity of MMP2 and MMP9 was restrained by TIPE1 in BGC823 cells, which may partially explain that TIPE1 can inhibit migratory and invasive behaviours in gastric cancer cells." (PMID 28994231, 2018). "Recent study showed that MMP-2 and MMP-14 could be candidates for molecular markers of gastric cancer." (PMID 29358963, 2017). "In this study, a total of 971 DEGs and 15 hub genes were selected, and BGN, MMP2, COL1A1 and FN1 might be the core genes of gastric cancer." (PMID 29050278, 2017). "Grhl2 reduces the expression of MMP-2, MMP-7 and MMP-9, which may partly explain the inhibitory effect of Grhl2 on invasion and migration of gastric cancer." (PMID 28067907, 2017). "In gastric cancer, asporin contributes to metastasis through EGFR and ERK-CD44/MMP-2 pathways." (PMID 27705916, 2016). "In our study, we found that transfection of HIF-1α-induced-miR-421 significantly down regulated the epithelial biomarker E-cadherin and up regulated N-cadherin, Fibronectin, Vimentin, Snail, Slug, Twist, MMP-2, and MMP-9 in cisplatin treated gastric cancer cell lines." (PMID 27016414, 2016). "In an additional proof-of-principle approach, we measured the expression of MMP2, MMP7 and MMP9 in MKN45 gastric cancer cells before and after treatment with the mTOR inhibitor rapamycin to investigate the putative link between mTOR signalling and MMP expression in gastric cancer." (PMID 26652716, 2015). "We propose that these results may apply to a number of additional cancer types other than gastric cancer, as CD147 and MMP-2 are frequently upregulated in numerous other cancer types as well." (PMID 24959277, 2014). "The results of the present study demonstrated the potential of COS in suppressing gastric cancer metastasis, and that the CD147/MMP-2 pathway may be involved as the key mechanism of its anti-metastatic effect." (PMID 24959277, 2014). "MMP-2 overexpression was found in a large proportion (94%) of the gastric cancer tissues compared with the matched non-cancerous tissues." (PMID 24959277, 2014). "Overall, our findings have demonstrated the potential of COS in suppressing gastric cancer metastasis and that the CD147/MMP-2 pathway may be involved as the key mechanism of its anti-metastatic effect." (PMID 24959277, 2014). "Moreover, upregulation of FENDRR has the effect of suppressing gastric cancer cell migration and invasion in vitro by targeting FN1 and MMP2/MMP9." (PMID 25167886, 2014).
gastric cancer (continued). "On the other hand, gastric carcinoma tissues strongly express PI3K p85α and p-AkT, and targeted blockade of the PI3K pathway inhibits gastric carcinoma growth and metastasis through downregulation of Ki-67 and MMP-2 expression." (PMID 25003395, 2014). "CAFs may promote gastric cancer cell migration and invasion via upregulating TAGLN and TAGLN induced MMP-2 production." (PMID 23510049, 2013). "Therefore, we examined the effect of coronin 3 knockdown or up-regulation on the expression of MMP-9, cathepsin K (based on the results of the PCR array), MMP-2, TIMP-1 and TIMP-2 in gastric cancer after infection." (PMID 22974233, 2012). "The data showed that the expression levels of MMP-2 and MMP-9 significantly decreased in the CTGF knockdown stable cell lines (PSC1 and PSC2), suggesting that this downregulation of MMP-2 and MMP-9 contributed to the reduced invasion of the CTGF knockdown stable gastric cancer cells." (PMID 21955589, 2011). "CD147 expression was gradually increased from normal mucosa to carcinomas through hyperplastic or metaplastic mucosa of the stomach, and its expression was positively correlated with tumor size, depth of invasion, lymphatic invasion and expression of ki-67, MMP-2, MMP-9 and VEGF in gastric cancer." (PMID 20525232, 2010). "As negative regulators in Wnt signaling, Secreted Frizzled-Related Proteins (SFRPs) are downregulated in a series of human cancers; and specifically, some matrix metalloproteinases (MMPs), including MMP-2, MMP-7, MMP-9 and MT1-MMP, are frequently overexpressed in gastric cancer." (PMID 19586554, 2009). "And levels of MMP-2 and MMP-9 are also found elevated in plasma of gastric cancer patients." (PMID 19586554, 2009). "A decade ago, we were the first to report that the levels of matrix metalloproteinase (MMP)-2 and MMP-9 in human gastric carcinoma tissues were enhanced and related to the survival of the patients, using a simple but laborious zymography technique in a relatively small group of patients." (PMID 16538217, 2006). "MMP-2 (gelatinase A), MMP-9 (gelatinase B), MMP-7 (matrilysin) and MMP-14 (MT1-MMP) are over-expressed in human gastric cancer." (PMID 12085177, 2002). "In the case of MMP-2, we do not have studies to which we could relate our results, but in gastric cancer and thyroid cancer, this marker acquired better diagnostic parameters than routine markers." (PMID 38892452, 2024). "However, there have been no reports about the correlation of MMP-2 and GV1001 in PDAC, while combined detections of telomerase activity and MMP-2 protein have been suggested as a risk factor of recurrence in gastric cancer." (PMID 37903909, 2024). "Dihydroartemisin downregulated PCNA and MMP-2, mediated by p16-Cyclin D1/CDK4-Rb pathway, suppresses the cell growth and metastasis of human gastric cancer (GC) cells." (PMID 39161904, 2024). "In addition, the absence of CDK5RAP3 in gastric cancer cells allows macrophages to secrete more MMP2 to promote the epithelial-mesenchymal transition (EMT) process of gastric cancer cells, thereby enhancing the invasion and migration ability." (PMID 35999359, 2023). "Upon the analysis of the TCGA dataset of 415 human gastric cancer tissue samples and 34 normal stomach samples, a dramatic increase in the mRNA levels of β-catenin (CTNNB1) and its downstream target genes, such as cMyc, CyclinD1 (CCND1), and MMP2, was observed in human gastric cancer tissue samples." (PMID 36551233, 2022). "Due to the great potential of these three markers (HER-2, MMP-2, and MMP-9) in the prognosis and treatment of advanced stages of gastric cancer, and the absence of investigations directly comparing MMP-2 andMMP-9 with HER-2 expression, we decided to evaluate this subject." (PMID 33773545, 2021).
gastric cancer (continued). "In gastric cancer (GC), SIRT1 silencing or inhibiting its activity by EX527 enhances expression of FOXO1, pro-apoptotic BAX, and E-cadherin, whereas the expression of Ki67, Cyclin D1, anti-apoptotic Bcl-2, Vimentin, MMP-2 and MMP-9 are downregulated, suggesting SIRT1 involvement in GC progression." (PMID 34769241, 2021). "It was also reported that MMP2 in renal carcinoma cells, MMP9 and MMP14 in osteosarcoma cells could increase soluble MICA and MMP9 specific inhibitor could increase MICA/B and ULBP2 in some kinds of gastric cancer cells." (PMID 34253166, 2021). "Indeed, in MKN45 gastric cancer cells, PAK1 silencing decreased mRNA levels and activity of MMP2 while PAK1 overexpression induced increased mRNA expression and increased activity of MMP2 leading to higher invasive properties." (PMID 34066419, 2021). "Similarly, CCL20/CCR6 binding leads to MMP2 upregulation via JAK2/STAT3 and CrkL-Erk1/2 pathways, and MMP9 upregulation through the activation of PKC-α, src, Akt, and NF-κB pathways in breast and gastric cancer." (PMID 33414786, 2020). "Secreted matrix metallopeptidase-2 (MMP-2) and urokinase-type plasminogen activator surface receptor (uPAR) have been demonstrated to activate focal adhesion kinase (FAK), which acts as an executioner of Bcl-w-dependent invasive phenotype of gastric cancer cells." (PMID 33364236, 2020). "The enzymatic activities of MMP2 and MMP3 increased (MMP2 rs2285053 CC: 888.60 vs. CT: 392.00, p <0.0001; MMP3 rs679620 AA: 131.10 vs. GG: 107.74, p=0.015), whereas those of MMP8 decreased (MMP8 rs1940475 TT: 133.78 vs. CC: 147.54, p=0.011) in gastric cancer tissues." (PMID 29285307, 2017). "Therefore, we tested the changes of MMP-2, MMP-7 and MMP-9 after Grhl2 overexpression in both SGC7901 and MKN45, so as to preliminarily clear the possible mechanisms by which Grhl2 inhibits invasion and migration of gastric cancer." (PMID 28067907, 2017). "Importantly, YY1 directly bond to MMP-14 promoter to increase its expression, resulting in elevated levels of VEGF and active MMP-2, but not of Snail, in gastric cancer cells." (PMID 28827574, 2017). "The current study identified that the inhibitory effect of KAI1 expression on the cell migration and invasion of gastric cancer was not mediated by HIF-1α, MMP-2 and MMP-9, but may be associated with the reduction in uPA and bFGF expression." (PMID 26622792, 2015). "In summary, an association between the presence of MMP2 and MMP7 proteins and (p-)mTOR expression in gastric cancer could not be confirmed." (PMID 26652716, 2015). "However, the expression and the activity of MMP-2/-9 in gastric cancer cells remained unaffected by Tob1 overexpression (data not shown)." (PMID 22710759, 2012). "MMP-2 (Hs.111301) expression has significant correlation with tumor invasion, tumor differentiation and lymph node metastases; MMP-2 may participate in the development of lymph node micrometastasis of gastric carcinoma." (PMID 17559667, 2007). "Furthermore, EMMPRIN transfection of tumour cells or treating tumour cells with the recombinant protein increased the expression of MMPs, especially MMP-2, as also evidenced by the positive correlation of EMMPRIN expression with MMP-2 and MMP-9 expression in our cases of gastric carcinoma." (PMID 17088917, 2006). "In the same way, we found that COL4A1 silence downregulated the expressions of Ki67, PCNA, MMP2, MMP9, N-cadherin and Vimentin but promoted E-cadherin expression in MKN-45 cells, revealing that COL4A1 silence could help to suppress the proliferation, metastasis and EMT in gastric cancer." (PMID 35297303, 2022). "Furthermore, co-overexpression of RAGE, Sp1, and MMP2 and accumulation of AGEs in cancer tissues were found in invasive cancer tissues, which suggested that the accumulation of glucose-derived AGEs may contribute to gastric cancer progression by regulating the expression of RAGE, Sp1, and MMP2." (PMID 29262634, 2017).
gastric cancer (continued). "We also found that the induction of FENDRR potently reduced the activity of MMP2/MMP9 in GC cells, and inhibition of FENDRR contributed to the activation of MMP2/MMP9, corroborating our earlier finding that FENDRR protected against gastric cancer cell metastasis." (PMID 25167886, 2014). "Similar results obtained in HCC and CCA patients were found in other cancers such as patients with gastric cancer, colorectal cancer, and pancreatic cancer: a significant negative correlation was found between RECK and MMP-2/MMP-9 expression." (PMID 38139236, 2023). "Although coordinated expression of legumain and MMP-2 was observed in gastric cancer tissues, there is no direct evidence yet that AEP mediates the activation of MMP-2 in GC, as it does in BC." (PMID 34068767, 2021). "In the present study, Grhl2 reduces MMP-2, MMP-7 and MMP-9 expression, which is partly explained by the mechanism by which Grhl2 inhibits gastric cancer cell invasion and migration, but this is obviously not enough." (PMID 28067907, 2017). "MMP2, MMP7 and MMP9 have been most extensively investigated in gastric cancer, but never previously in a direct comparison and in association with mTOR expression." (PMID 26652716, 2015). "While the data presented here is focused on human circulating B-lymphocytes our conclusions are supported by studies in gastric cancer where MMP-7 and MMP-2 expression did not correlate with mTOR activation and Rapamycin failed to decrease MMP-7 secretion despite decreasing mTOR phosphorylation." (PMID 28634370, 2017).
prostate carcinoma (289 papers, 2003 to 2026). A carcinoma that arises from epithelial cells of the prostate gland. "Matrix metalloproteinase 2 (MMP-2) is a type IV collagenase; its expression in prostate cancer cells is associated with a worse prognosis." (PMID 40427006, 2025). "Hypomethylation of the promoter regions of tumor-promoting genes such as uPA and matrix metalloproteinase-2 (MMP-2) have been associated with tumor growth in prostate cancer PC-3 cell line, which can be reverted by SAMe treatment." (PMID 39941901, 2025). "Polymorphism of the MMP2-1306gene plays a significant role in carcinogenesis, in particular,the C variant is associated with a protective role in the developmentof prostate cancer, its frequencyis higher among patients with bronchial asthma." (PMID 39027126, 2024). "Other studies also show similar results with GHRH antagonist treatment in prostate cancer cells, associating reduced MMP2 and 9 activity with reduced tumour cell motility and invasiveness." (PMID 39456984, 2024). "Namely, it was suggested that MMP2 has diagnostic, prognostic, risk stratification, and risk of disease biomarker potential in prostate cancer." (PMID 38255186, 2023). "Several MMPs have been implicated in prostate cancer growth and progression, for example increased MMP-2 expression is associated with advanced disease and a highly reactive stroma." (PMID 36671452, 2022). "SENP1 is linked to prostate cancer progression because SENP1 regulation of matrix metallopeptidase 2 (MMP2) and matrix metallopeptidase 9 (MMP9) through the hypoxia-inducible factor 1-alpha (HIF-1α) signaling pathway promotes progression." (PMID 35408841, 2022). "Consistently, inhibition of AKT diminishes the expression of bone sialoprotein (BSP), OPN, pro-invasive matrix metalloproteinase-2 (MMP2), and αvβ3-integrin in prostate cancer cells, which are all proteins associated with the occurrence of bone metastases." (PMID 34064589, 2021). "Consist with the previous study, treatment with downregulation of DKK-3 facilitated malignant phenotypes of prostate cancer cells, upregulating MMP-2 and MMP-9, and even reversed the effect caused by overexpression of LINC00261." (PMID 33013201, 2020). "The relevance of increased MMP2 activity for prostate cancer cell invasion is underlined by the ability of the MMP2 inhibitor ARP100 to reduce the pro-invasive effects of DKK3-silenced WPMY-1 CM in PC3 cells." (PMID 29858602, 2018). "The rs243865 in MMP-2 was previously reported to correlate with increased prostate cancer risk among Indian population, however study conducted in Iran did not confirm this finding." (PMID 30036379, 2018). "In our meta-analysis, it is indicated for the first time that the MMP2 rs243865 SNP is significantly correlated with the risk of prostate cancer." (PMID 29069837, 2017). "It has been suggested that the MMP2 gene is strongly associated with the development of prostate cancer by affecting cell growth, the production of cell junction proteins, such as collagens, and the pathogenesis of metastasis and invasion." (PMID 29069837, 2017). "The overall analysis showed that the MMP-2-1306 C/T polymorphism increased the risk of prostate cancer under CT vs. CC model (OR = 1.78, 95% CI = 1.33–2.38) and TT+CT vs. CC model (OR = 1.62, 95% CI = 1.24–2.12)." (PMID 29249982, 2017). "In summary, we show that the MMP2 −1306C/T polymorphism is a susceptibility locus for prostate cancer." (PMID 29069837, 2017). "Our meta-analysis results suggest that MMP2 rs243865 polymorphisms are significantly associated with higher risk of prostate cancer." (PMID 29069837, 2017). "In this study, we performed a literature review and conducted a meta-analysis of the pooled results of relevant data from studies exploring the association between MMP2 genetic polymorphisms and the risk of prostate cancer." (PMID 29069837, 2017). "Numerous investigations have addressed the correlation between MMP2-1306C/T polymorphism and prostate cancer (PCa) susceptibility." (PMID 28445160, 2017).